LCN2 (lipocalin 2)
Diseases named in the same sentence as LCN2 in open-access papers (continued):
Sharing a sentence is not in itself a finding about the gene and the disease.
ischemic stroke (50 papers, 2015 to 2025). A stroke disorder caused by obstruction of blood flow to the brain, due to thrombotic (local blood clot formation) or embolic (due to a blood clot or other material traveling from another site) event. "This study demonstrated that higher circulating LCN2 level was associated with an increased risk of early clinical worsening and 90‐day unfavorable outcomes in ischemic stroke patients." (PMID 36974345, 2023). "In summary, serum LCN2 is up-regulated after ischemic stroke and LCN2 is strongly associated with depression." (PMID 37543589, 2023). "Neutrophil gelatinase-associated lipocalin (LCN2) is highly expressed after ischemic stroke and is involved in neuron death and brain injury." (PMID 35053263, 2022). "Upregulated LCN2 is associated with a variety of central nervous system diseases, such as acute brain injury ischemic stroke, hemorrhagic stroke, traumatic brain injury, and neurodegenerative brain diseases such as Alzheimer’s disease (AD), Parkinson’s disease (PD), and vascular dementia (VaD)." (PMID 40025014, 2025). "Research on ischemic stroke has suggested that acute elevation of LCN2 in both blood and cerebrospinal fluid (CSF) are associated with neuroinflammation by promoting the infiltration of peripheral neutrophils and activation of pro-inflammatory glial cells 78-80." (PMID 40083945, 2025). "Furthermore, elevated LCN2 levels in plasma are associated with poor neurological scores and estimated glomerular filtration rate (eGFR) at 3 months in ischemic stroke patients." (PMID 36187347, 2022). "Moreover, LCN2 released from astrocytes and infiltrating neutrophils may cause additional neuronal damage after ischaemic stroke." (PMID 25702801, 2015). "In view of the important role of LCN2 in CIRI, this article reviews the mechanism of LCN2, aiming to provide new ideas and methods for the treatment of ischemic stroke." (PMID 40182140, 2025). "Their study shows that LCN2 is not only an important regulator of astrocyte classical activation after ischemic stroke, but also likely a key determinant of its activation status." (PMID 40182140, 2025). "NHE1 protein represents a potential target for mitigating Lcn-2-mediated neurotoxicity after ischemic stroke." (PMID 38533497, 2024). "Lcn-2 exerts adverse effects on astrocyte polarization in ischemic stroke, manifested by increased infarct volume and impaired neurological function." (PMID 38533497, 2024). "In our study, we were able to support the assumption that LCN2 has the potential to predict early outcomes after ischemic stroke." (PMID 36974345, 2023). "Extensive studies have found that after ischemic stroke, LCN2 is not only up-regulated in the central nervous system (CNS), but also significantly increased in serum." (PMID 37543589, 2023). "LCN-2 and B2M correlate with oxidative stress, which plays an important role in the pathogenesis of ischaemic stroke." (PMID 37155257, 2023). "It is reported that elevated levels of LCN2 in human plasma 1–3 days after ischaemic stroke, and plasma LCN2 still has a high expression level in the subacute phase." (PMID 37543589, 2023). "Second, LCN2 was involved in the expression of pro‐inflammatory cytokines, chemokines, and adhesion molecules after ischemic stroke." (PMID 36974345, 2023). "Relevant basic studies have shown that after ischemic stroke, elevated LCN2 activates various inflammatory pathways in glial cells, leading to glial cell proliferation, cytokine production and enhanced inflammatory response, so that neuroinflammation persists." (PMID 37543589, 2023). "In the in vitro model of ischemic stroke, the maximum level of astrocyte LCN2 expression appeared at 12 h after OGD/R." (PMID 37353794, 2023). "Studies have revealed that early serum and brain LCN2 elevations have become promising biomarkers for patients with ischemic stroke." (PMID 36187347, 2022).
ischemic stroke (continued). "Another study found that miR-138-5p-enriched exosomes alleviated neurological impairment by accelerating the proliferation of astrocytes and suppressing inflammation by targeting lipocalin 2 in ischemic stroke mice." (PMID 35053263, 2022). "The results demonstrated that elevated LCN2 is essential in early brain injury after ischemic stroke." (PMID 36187347, 2022). "LCN2 was found to act as a beneficial factor by sending a “help me” signal after an ischemic stroke." (PMID 36187347, 2022). "LCN-2 expression following ischemic stroke was reportedly increased both in the sera and brain, where it was localized to infiltrating neutrophils, cerebral endothelium, and a subset of astrocytes." (PMID 35493318, 2022). "Numerous LCN2+ neutrophils were detected in the infarct hemisphere in the LCN2 positive vessels at 23 h after tMCAO, indicating that blood vessels are the major pipelines for LCN2+ neutrophils to infiltrate into injury sites after ischemic stroke." (PMID 36187347, 2022). "Targeting astrocytic NHE1 is beneficial to reduce LCN2-mediated neurotoxicity after ischemic stroke." (PMID 35440572, 2022). "Further, upregulated genes included Gfap, Lcn2, and Serpina3n, which have been validated as specific markers of reactive astrogliosis in ischemic stroke and LPS-induced neuroinflammation." (PMID 34819339, 2022). "In ischemic stroke, pro-inflammatory mediators regulated by LCN-2 play a key role in ischemia-reperfusion injury." (PMID 35493318, 2022). "A recent study suggested that lipocalin-2 regulated myelin phagocytosis in an ischemic stroke mouse model." (PMID 36558562, 2022). "Altogether, our findings suggest that LCN2/LRP1 regulates astrocyte-mediated myelin phagocytosis in a mouse model of ischemic stroke." (PMID 35241660, 2022). "In summary, our study provided appealing evidence for NHE1 in the regulation of reactive astrocyte function by modulating the expression and release of LCN2 protein after ischemic stroke." (PMID 35440572, 2022). "In mice models of ischemic stroke induced by transient middle cerebral artery occlusion (tMCAo), serum level of LCN2 was acutely induced after tMCAo and was reduced at 48–72h post-tMCAo." (PMID 34179014, 2021). "Exosomes derived from miR-138-5p-overexpressing bone marrow-derived mesenchymal stem cells confers neuroprotection to astrocytes following ischemic stroke via the inhibition of LCN2." (PMID 34215174, 2021). "In this study, we analyzed LCN2 expression in hypoxic rat brain tissue after ischemic stroke and in astrocyte cell cultures receiving standardized hypoxic treatment." (PMID 30871254, 2019). "The results indicated a novel pattern of astrocyte activation after ischemic stroke and lipocalin-2 (LCN2) plays a key role in polarizing and activating astrocytes." (PMID 31426811, 2019). "In the present study, we have studied the time course of peri-infarct LCN2 expression using a well-established rat ischemic stroke model, i.e., transient middle cerebral artery occlusion (tMCAO) model." (PMID 30871254, 2019). "From previous data in animal models of cerebral ischemia, lipocalin-2 (LCN2), a protein related to neutrophil function and cellular iron homeostasis, is supposed to have a value as a biomarker in ischemic stroke patients." (PMID 27152948, 2016). "Our study is the first to describe long-term expression kinetics of LCN2 in tMCAO, an animal model of ischemic stroke." (PMID 27152948, 2016). "In animal models of inflammatory brain injury, intracerebral hemorrhage and ischemic stroke, LCN2 upregulation occurred predominantly in astrocytes and, to a lesser extent, in neurons." (PMID 27152948, 2016). "The expression of LCN2 in in vitro cultured glial cells and in animal models has focussed attention to its putative use as a biomarker of CNS injury including ischemic stroke." (PMID 27152948, 2016).
ischemic stroke (continued). "To assess the time course of LCN2 induction after ischaemic stroke, we occluded the MCA for 1 hr and collected sera of wild-type (WT) and Lcn2−/− mice at 23 hrs after reperfusion." (PMID 25702801, 2015). "Several pathological conditions including bacterial infection, renal ischemia, spinal cord injury, and ischemic stroke trigger the release of LCN2." (PMID 25890235, 2015). "Previous studies demonstrated that the level of LCN2 in human plasma is elevated after ischemic stroke." (PMID 25890235, 2015). "Previous studies have shown that LCN2 plays a vital role in apoptosis and the plasma concentration of LCN2 is elevated in patients suffering from ischemic stroke." (PMID 25890235, 2015). "Here, we show that LCN2 was acutely induced in mice after ischaemic stroke and is an important mediator of reperfusion injury." (PMID 25702801, 2015). "Our results identify LCN2 as an acute-phase protein that mediates reperfusion injury after ischaemic stroke in mice." (PMID 25702801, 2015). "Previous studies demonstrated elevated levels of LCN2 in human plasma 1–3 days after ischaemic stroke 5,6." (PMID 25702801, 2015). "However, few data are available to date regarding the prognostic value of serum LCN2 in ischemic stroke patients." (PMID 36974345, 2023). "Herein, we performed a prospective study and aimed to evaluate whether circulating LCN2 levels were correlated with clinical outcomes in patients with ischemic stroke." (PMID 36974345, 2023). "The role of LCN2 in iron transport after ischemic stroke requires further study." (PMID 36974345, 2023). "Thus, targeting astrocytic NHE1 protein is beneficial to reduce LCN2-mediated neurotoxicity after ischemic stroke." (PMID 35440572, 2022). "Notably, the infarct volume, neurological deficits, immune infiltrates, and pro-inflammatory molecules (IL-1β, TNF-α, CCL2, and CXCL1) were attenuated in LCN2–/– mice after ischemic stroke." (PMID 36187347, 2022). "In our study, we observed that ischemic stroke-induced neurodegeneration (loss of NeuN+ and GRP78+ neurons) in the peri-lesion cortex and striatum was associated with increase in reactive astrogliosis (elevated GFAP+/LCN2+ astrocyte counts)." (PMID 35440572, 2022). "Therefore, the current study investigated if LCN2 specific antibodies neutralized LCN2 and diminished neuroinflammation and neurodegeneration after ischemic stroke." (PMID 32872405, 2020). "In a first set of experiments, we aimed at investigating whether ischemic stroke induces an increase in LCN2 expression within the peri-infarct cortical brain area." (PMID 30871254, 2019). "Our findings suggest that elevated LCN2 in the blood after ischemic stroke might affect endothelial function, in part by reducing damage to endothelial junctional proteins and maintain blood-brain barrier integrity." (PMID 31269059, 2019). "Therefore, we examined LCN2 expression in the ischemic brain in an animal model and measured plasma levels of LCN2 in ischemic stroke patients." (PMID 27152948, 2016). "To determine whether LCN2 is induced in brain tissues after ischaemic stroke, we analysed brain homogenates of WT and Lcn2−/− mice before and after tMCAO." (PMID 25702801, 2015). "This raises the intriguing possibility that LCN2 inhibitors or anti-LCN2 antibodies could be important therapeutic candidates to modulate post-ischaemic inflammation in patients with ischaemic stroke." (PMID 25702801, 2015). "The plasma concentration of LCN2 is increased in patients after ischaemic stroke 5,6." (PMID 25702801, 2015). "Elevated plasma levels of LCN2 have been detected in patients suffering from ischaemic stroke 5,6." (PMID 25702801, 2015). "LCN2 induction is observed in various neurological conditions, including multiple sclerosis, chronic inflammatory pain, neuropathic pain, Alzheimer’s disease, Parkinson’s disease, vascular dementia, ischemic stroke, intracerebral hemorrhage, stab wound injury, and traumatic brain injury." (PMID 38991663, 2024).
ischemic stroke (continued). "Also, many genes encoding chemokines, cytokines and chemokine receptors, which are involved in neuroinflammatory processes in ischemic stroke, were regulated, including Cxcr2 in endothelial cells, Ccl5, Il11 and Il6 in pericytes, Lcn2 in astrocytes and pericytes, and Il1rn in microglia." (PMID 35752654, 2022). "However, how RA regulate LCN2 expression in ischemic stroke conditions remains to be established." (PMID 35440572, 2022). "In a mouse model of ischemic stroke induced by middle cerebral artery occlusion (MCAO), the expression of lipocalin-2 (LCN2) in astrocytes markedly increases after 24 hours, which significantly promotes neuroinflammation." (PMID 40083546, 2025). "It not only suppressed inflammatory response states in astrocytes following ischemic stroke by targeting lipocalin 2 (LCN2) but also inhibited the target of caspase-9 and apoptosis-related cysteine peptidase (Casp9) against ischemic stroke (IS) injury." (PMID 37841310, 2023). "However, some studies revealed that LCN2 might also act as a beneficial factor in ischemic stroke." (PMID 36187347, 2022). "To confirm the cellular distribution of LCN2, we subjected primary mixed neuronal-glial cultures to OGD, an in vitro model of ischaemic stroke." (PMID 25702801, 2015). "Following ischemic stroke, reactive astrocytes in nonischemic areas of the corpus callosum upon injury express Lcn-2 and acquire a phagocytic phenotype capable of uptaking myelin phospholipids." (PMID 38533497, 2024). "In summary, this study performed in the Chinese population demonstrated that increased serum LCN2 may be an independent predictor of END and 90‐day poor outcome after ischemic stroke." (PMID 36974345, 2023). "A recent study also showed a non-disruptive blood-brain barrier dysfunction by Lcn2 following ischemic stroke as shown in human endothelial cells." (PMID 32622362, 2020). "In conclusion, cerebral ischemic stroke may exacerbate cancer progression by increasing LCN2 expression in PMN-MDSCs, which turns out to be a promising therapeutic target to suppress cancer progression after ischemic stroke." (PMID 32153594, 2020). "However, the percentage of LCN2+ CD45+CD11b+Ly6GlowLy6Chi cells did not change significantly in the peripheral blood of cancer-bearing mice after ischemic stroke." (PMID 32153594, 2020). "However, the precise role of LCN2 during the different phases of ischemic stroke, i.e., acute and chronic phase, has not yet been defined." (PMID 30871254, 2019).
prostate carcinoma (47 papers, 2011 to 2026). A carcinoma that arises from epithelial cells of the prostate gland. "In vitro and in vivo studies have shown that LCN2 promotes cell invasion and migration and distant metastasis in prostate cancer via the ERK signaling pathway, causing up-regulation of the SLUG transcription factor to induce the EMT." (PMID 34062746, 2021). "We further investigated the effect of CXCL1 and LCN2 on prostate cancer using in vivo and in vitro models, and explored the underlying signal transduction pathways." (PMID 31500632, 2019). "We used an in vitro model of ER stress to test the hypothesis that ER stress and Lcn2 upregulation are causally linked in prostate cancer cells, as a first step in an effort to elucidate the broad role of constitutive ER stress in cancer cells." (PMID 21649922, 2011). "To test whether transcription of Lcn2 is associated with activation of NF-κB in prostate cancer cells, we created a transgenic TC1 cell line, which carries an NF-κB reporter plasmid (TC1.pNGL) containing an enhanced green fluorescent protein (EGFP)-luciferase fusion gene." (PMID 21649922, 2011). "The positive correlation between higher concentration of LCN2 and prostate cancer invasiveness in in vivo and in vitro studies." (PMID 39941741, 2025). "The authors show that SERPINA3 and LCN2 have osteogenic and tumor‐suppressive roles at sites of bone metastases in osteoblastic prostate cancer." (PMID 37408474, 2023). "Since the precise role of LCN2 in prostate cancer (PCa) is poorly understood, we aimed to elucidate its functions in PCa in vitro." (PMID 35053376, 2022). "A previous in vitro study showed that lipocalin-2 gene was one of the highly amplified genes in paclitaxel-resistant PC-3-TxR cell obtained from parent prostate cancer cell line (PC-3)." (PMID 33542838, 2021). "In their study, lipocalin-2 was highly expressed in 37% of tissues of prostate cancer according to normal prostate tissues." (PMID 33542838, 2021). "There are only two studies investigating the relationship between prostate cancer and lipocalin-2 expression in the current literature." (PMID 33542838, 2021). "It is clear that further studies are needed to evaluate the predictive and prognostic role of lipocalin-2 in prostate cancer patients." (PMID 33542838, 2021). "In relation to the prostate cancer cell lines there are data proving the contribution of Lcn2 in prostate cell proliferation, however, this effect is dependent on the prostate cell type." (PMID 31671654, 2019). "LCN2 promotes breast and prostate cancer progression by inducing epithelial to mesenchymal transition (EMT) through the ERα/Slug axis." (PMID 30517191, 2018). "In the other original study on prostate cancer, the expression levels of 35 genes including HP and LCN2 were found to be correlated with overall survival (OS)." (PMID 28771541, 2017). "We have previously demonstrated that LCN2 plays a role in facilitating cell migration and invasion in prostate cancer through inducing EMT by the axis of ERK/SLUG." (PMID 27602760, 2016). "LCN2-mediated cell migration has been reported in other tumors such as breast and prostate carcinomas." (PMID 27168162, 2016). "We have previously reported that LCN2 is closely related to the invasiveness of cells of prostate cancer." (PMID 27602760, 2016). "Knockdown of LCN2 suppresses the invasion of prostate cancer cells through downregulation of MMP-2 and MMP-9." (PMID 25940797, 2015). "Other genes act as tumor suppressors, such as IGFBP3, which inhibits prostate cancer growth through suppression of angiogenesis, and LCN2, which increases the expression of E-cadherin and suppresses cell invasiveness." (PMID 22328933, 2012). "We interrogated Lcn2 regulation in murine and human prostate cancer cells undergoing pharmacological and physiological ER stress, and tested UPR and NF-κB dependence by using pharmacological inhibitors of these signaling pathways." (PMID 21649922, 2011).